FBP1 (fructose-bisphosphatase 1)
Diseases named in the same sentence as FBP1 in open-access papers (continued):
Sharing a sentence is not in itself a finding about the gene and the disease.
cancer (continued). "To investigate whether circFNDC3B-218aa could inhibit cancer progression by enhancing FBP1, we transfected CC cells with siFBP1 and circFNDC3B-218aa overexpression plasmid." (PMID 32241279, 2020). "Notably, PPP remains active via upregulation of TIGAR in the FBP1-loss basal-like subset, indicating the importance of PPP in catabolic cancer metabolism." (PMID 32927665, 2020). "Given that upregulation of PD-L1 expression in antigen-presenting cells (APCs) is also very important for cancer immune evasion, whether the FBP1-involved mechanism accounts for this upregulation in a paracrine dependent fashion warrants further investigation." (PMID 31938049, 2020). "FBP1 plays an important role in the tumorigenesis and progression of several cancers." (PMID 33232284, 2020). "FBP1 is also considered to be a potential marker of cancer and a prognostic marker." (PMID 33232284, 2020). "Silencing FBP1 can significantly promote the proliferation and metastasis of cancer cells." (PMID 33232284, 2020). "Given that PD-L1 is a key immune checkpoint molecule and it is often deregulated in human cancers 3-5, 15, 35, we sought to determine whether FBP1 expression influence cancer immunity by regulating PD-L1 expression in cancer cells." (PMID 31938049, 2020). "In addition, Snail1 represses pro‐apoptotic genes and the FBP1 gene, thus promoting the metabolism of cancer stem cells." (PMID 29729076, 2018). "The specific mechanism underlying FBP1 downregulation is associated with promoter methylation and copy-number loss, leading to decreased FBP1 mRNA expression or post-transcriptional modification of FBP1 protein mediated by MAGE-TRIM28 complex, which results in FBP1 degradation in cancer cells." (PMID 30201002, 2018). "Previous studies also show that FBP1 is epigenetically silenced in human cancers." (PMID 28394358, 2017). "Our study also demonstrates that MAGE-TRIM28 regulation of FBP1 degradation affects the Warburg effect and HCC progression, suggesting that MAGE-TRIM28 regulates reprogramming of cancer cell metabolism by causing protein degradation of multiple metabolic regulators including FBP1." (PMID 28394358, 2017). "Thus, our data not only identify TRIM28 as an E3 ligase of FBP1, but also suggest that TRIM28-regulated reprogramming of cancer cell metabolism is mediated, at least in part, through FBP1 degradation in HCC cells." (PMID 28394358, 2017). "Thus, our findings and those from other reports suggest that MAGE-TRIM28 ligase regulates multiple metabolic regulators (for example, AMPK and FBP1) to reprogram cancer cell metabolism." (PMID 28394358, 2017). "In cancer, down-regulation of FBP1 can result in GAPDH accumulation within the cytoplasm and may also cause translocation of excess GAPDH to the nucleus." (PMID 23620736, 2013). "By contrast, FBP1 was downregulated in the ER− cancers, which could accelerate glucose metabolism and thereby contribute to ER− cancers through the anaerobic glycolysis subpathway." (PMID 23875016, 2013). "Down-regulation of FBP1 in cancer cells has been reported recently." (PMID 23620736, 2013). "We further demonstrated that treatment with the demethylation reagent Aza upregulated FBP1 expression in lowly expressed cancer cells and the methylation status was verified by genomic sequencing, indicating that DNA hypermethylation mediated FBP1 inactivation." (PMID 22039417, 2011). "Thus FBP1 may exert different immune effects in different cancer types by regulating the function of NK cells." (PMID 40100307, 2025). "However, the relationship between EGFR mutations and Gefitinib target genes (FBP1, SBK1, and AURKA) warrants further investigation, and cancer tissues were collected to confirm the relationship between the risk model and nomogram and the prognosis of LUAD patients in the future." (PMID 37737707, 2023). "Furthermore, the expression of ALDOA and FBP1 also showed similar trends in multiple cancer stages." (PMID 35404841, 2022).
cancer (continued). "Thus, in addition to being diagnostic markers, these molecules may also regulate FBP1 and ALDOA during cancer progression." (PMID 35404841, 2022). "The mechanism of the downregulation may associate with DNA hypermethylation of its promoter and copy number loss 28, 45, histone deacetylation due to the deregulation of HDACs 33 or the post-transcriptional modification mediated by MAGE-TRIM28 leading to the degradation of FBP1 in cancer cells." (PMID 31938049, 2020). "For another example, FBP1, an estrogen signaling responsive gene that encodes the enzyme catalyzing the reverse reaction of PFKP, was upregulated in the ER+ cancers, which could elevate the activity of the oxidative branch of the pentose phosphate pathway and thereby contribute to cancers." (PMID 23875016, 2013). "Recent studies have shown that FBP1 overexpression could suppress glycolysis in cancer cells." (PMID 24063558, 2013). "Analysis on the role of FBP1 in GBM based on the relevant data and the pan-cancer level of FBP1 revealed a relatively higher level of FBP1, especially in GBM (p < 0.05)." (PMID 39902328, 2025). "Epigenetic changes dysregulate HIF-1α and metabolic enzymes like fructose-bisphosphatase FBP1, PKM, and Lactate dehydrogenase A (LDHA) in CAFs, fueling cancer growth." (PMID 40230452, 2025). "Thus, inhibiting glycolysis by increasing FBP1 expression may play a crucial role in improving cisplatin sensitivity, and combination therapies targeting the glycolytic pathway are promising for the treatment of chemoresistant cancer cells." (PMID 40100307, 2025). "To further investigate the role of FBP1 in mediating the cancer stem cell phenotype, we generated stable knockdown PC9 cells with reduced FBP1 expression." (PMID 38349431, 2024). "To enhance our comprehension of FBP1 in NSCLC, we conducted an investigation into the role of FBP1 in maintaining the phenotype of cancer stem cells." (PMID 38349431, 2024). "We also identified a series of metabolic rate‐limiting enzymes related to genomic alteration and prognosis, such as SQLE and FBP1, which were reported as CNV‐expression correlated genes and played important roles in human cancers." (PMID 36629054, 2023). "To investigate the relationship between FBP1 and ALDOA among cancers, we screened for prognostic value and candidate gene expression across cancers." (PMID 35404841, 2022). "The expression of FBP1 and TAPBPL was significantly high in BC tissues, and moderate expression of GPRC5C was found both in breast normal tissue and cancer tissue." (PMID 36358906, 2022). "This study explored the relationship between FBP1 and ALDOA across cancers and identified a significant correlation between LIHC and LUAD." (PMID 35404841, 2022). "There are approximately 98.2% methylation-regulated genes shared by at least two types of cancers, including 3,801 genes (e.g., HIST1H4F, FBP1 and CPEB4) shared across all cancers." (PMID 34464378, 2021). "Consistently, FBP1 overexpression obviously inhibited the expression of SOX2, OCT4, and NANOG, which regulated CSC-like property in various cancers." (PMID 34363022, 2021). "Of the 10 proteins, the preceding text showed that some studies identified RRM2, PLOD2, MKI67, MCM5, and CKD1 promoted cancer progression and FBP1, FBP2, ENO3, GPD1, and ASS1 inhibited cancer progression, which was consistent with our results." (PMID 33200655, 2020). "Our findings reveal FBP1 as an upstream inhibitor of STAT3 and uncover a new mechanism that regulates the function of STAT3 in cancer." (PMID 31938049, 2020). "At the same time, pan-cancer analysis also shows that PPM1A, DAPK1, FBP1, PYHIN1, ALPL and SMCHD1 have significant amplification in PCa." (PMID 30867653, 2019). "To investigate the functional phenotype of FBP1 in CCA cells, we assessed the expression of FBP1 using the GSE76297 dataset and found reduced FBP1 expression in cancer tissues compared with control normal tissues." (PMID 31383847, 2019).
cancer (continued). "Aberrant FBP1 expression weakened the anti-cancer progression of natural killer cells by destroying their normal metabolic capability and impairing viability, while its inhibition can restore natural killer cell function." (PMID 36494582, 2023). "Furthermore, circFNDC3B-218aa was proved to repress the cancer progression and EMT by moderating the suppressive effect of Snail on FBP1 in vivo and in vitro." (PMID 36793611, 2023). "Since DNMT1 is responsible for the resistance of cancer cells to PARP inhibitors, we investigated whether FBP1 regulates the sensitivity to PARP inhibitors via DNMT1." (PMID 34854226, 2022). "In pancreatic cancer, FBP1 inhibits the activation of ERK by gemcitabine via inhibiting the IQGAP1/ERK1/2 signaling pathway independent of its enzymatic activity, thereby enhancing the anti-cancer effect of drugs and overcoming drug resistance." (PMID 32038983, 2020). "Taken together, these data suggested that circFNDC3B-218aa could inhibit the cancer progression and EMT via alleviating the repressive effect of Snail on FBP1." (PMID 32241279, 2020). "High rates of FBP1 and FBP3 expression were observed in all cancer types." (PMID 19087307, 2008). "Therefore, the downregulation of FBP1 in NSCLC may lead to the overactivation of Notch signaling, thereby enhancing the cancer stem cell phenotype." (PMID 40100307, 2025). "Based on the relationship between FBP1 and ALDOA in patients and the related cellular distribution, we hypothesized that ALDOA and FBP1 coregulate specific and identical molecules to control cancer progression." (PMID 35404841, 2022). "Snail (SNAI1), a well-known inducer of cancer EMT, is critical in providing ATP and NADPH via suppression of several gatekeeper genes involving catabolic metabolism, such as phosphofructokinase 1 (PFK1), fructose-1,6-bisphosphatase 1 (FBP1), and acetyl-CoA carboxylase 2 (ACC2)." (PMID 32927665, 2020). "Furthermore, we speculated that circFNDC3B-218aa could inhibit the cancer progression and EMT via alleviating the repressive effect of Snail on FBP1." (PMID 32241279, 2020). "Previous studies identified that far upstream element-binding protein 1 (FBP1), a transcriptional regulator of c-Myc that is one of the most frequently aberrantly expressed oncogenes in various human cancers, including NPC, is an important biomarker for many cancers." (PMID 26469968, 2015). "To understand whether the relationship between ALDOA and FBP1 in patients was also reflected in cell lines, we conducted correlation analysis using the CCLE dataset, which is a complete analysis of the gene expression differences between multiple cancer cell lines." (PMID 35404841, 2022). "Increased ALDOA and decreased FBP1 levels are phenotypic characteristics in human cancers without the molecular explanation of how ALDOA and FBP1 regulate the FBP utilization." (PMID 36077431, 2022).
infection (17 papers, 2009 to 2026). The state of being infected such as from the introduction of a foreign agent such as serum, vaccine, antigenic substance or organism. "Following infection of mice, loss of Pck1 or Fbp1 function reduced lung fungal burdens, with loss of Pck1 causing a stronger reduction than depletion of Fbp1." (PMID 32265333, 2020). "We found that the fbp1Δ mutant strain can elicit superior protective Th1 host immunity, and a heat-killed fbp1 deficient strain (HK-fbp1) is a potent vaccine candidate that induces protection against infection with the virulent parental strain Cn-H99 in murine models." (PMID 39324785, 2024). "To evaluate these metabolic changes earlier during infection, we examined the abundance of Fbp1 and Lct at 6 and 9 dpi by qPCR." (PMID 34928716, 2022). "Next, we knocked down GATA4 level using lentivirus-mediated infection with a specific shRNA and assessed FBP1 protein expression in DPSCs." (PMID 31892855, 2020). "Decreased FBP1 expression was evident at 4 hours post-infection (h.p.i.), and FBP1 levels were significantly reduced by 8 and 10 hours post-infection." (PMID 27780225, 2016). "In contrast to FBP1, Cp was mostly present in the cytoplasm (lanes 5 and 7), and Cp levels increased through the course of infection." (PMID 27780225, 2016). "It was also of interest that we found transcripts of FBP1 to be up- regulated during WSSV infection with the highest level occurring at 48 h post-infection." (PMID 22428011, 2012). "Once infection is resolved, their population contracts to baseline levels, but by day 14 post‐infection, they undergo functional diversification, giving rise to Trem2+ Reg‐Ms and Fbp1+ Prolif‐Ms that promote inflammation resolution and tissue repair." (PMID 41271590, 2026). "EV-A71 induces the cleavage of FBP1 during the middle stages of infection." (PMID 38257775, 2023). "However, upon EV-A71 infection, FBP1 is redistributed in the cytoplasm, where most of the steps in viral replication take place." (PMID 38257775, 2023). "In addition, a 38-kDa protein band, likely a cleavage product (Cp) of FBP1, appeared at Hour 4 and reached a maximal level at Hour 6; moreover, a potential 30-kDa Cp of FBP1 appeared at 8 and 10 hours post-infection, demonstrating that EV71 infection destabilizes FBP1." (PMID 27780225, 2016). "TBEV-infection of hMNs increased the production of SAM, FBP1 and PEP in a time-dependent manner." (PMID 40517242, 2025). "Moreover, the expression levels of FBP1 and NICD1, along with the downstream markers of the NOTCH pathway, were detected at various time intervals subsequent to the infection of A549 and H1299 cells with FBP1 overexpression lentivirus." (PMID 38349431, 2024). "In the non-ECs fraction, Ad-P4HA1 infection slightly increased the P4HA1 protein level but did not change the protein levels of FBP1 and TET2." (PMID 38238754, 2024). "Surprisingly, Hsp27 knockout did not block FBP1 translocation after EV-A71 infection, suggesting that Hsp27 differentially regulates only a portion of the RNA binding proteins’ redistribution to the cytosol." (PMID 30814282, 2019). "The expression of FBP1(G371K)R can also rescue viral titers at 6 and 9 hours post-infection, but not to the same extent as FBP1R, and this indicates that cleavage of FBP1 and the additive effect from FBP11-371 plays a key role in virus growth." (PMID 27780225, 2016). "However, Hsp27 knockout did not affect the translocation of FBP1 after EV-A71 infection, indicating that the regulation of the RNA-binding protein cytosol redistribution is not general." (PMID 30814282, 2019). "We simulated the coexistence of FBP1 and FBP11-371 during the middle stage of infection by adding recombinant versions of both proteins to an in vitro IRES activity assay, and found that FBP11-371 can additively promote viral protein translation in a FBP1-dependent manner." (PMID 27780225, 2016).
infection (continued). "Furthermore, Ad-shP4HA1 infection did not affect protein levels of P4HA1, TET2, and FBP1 in the non-ECs fraction." (PMID 38238754, 2024).
kidney diseases (3 papers, 2019 to 2026). "On the other hand, three of the four representative genes in group 2 (AXDND1, FBP1, and MIR2278) are likely to be associated with kidney diseases." (PMID 37386009, 2023). "The other was characterized by genes associated with kidney disorders (AXDND1, FBP1, and MIR2278)." (PMID 37386009, 2023).
immune disorders (2 papers, 2023 to 2025). "In contrast, after treatment with QRHXD, the inflammatory state and immune disorders in RA patients were alleviated, reducing the body’s energy consumption and rendering FBP1 inactive." (PMID 40124380, 2025).
metabolic disorder (2 papers, 2024 to 2025). "Fructose-1,6-bisphosphatase (FBPase) deficiency is an autosomal recessive metabolic disorder caused by mutations in the FBP1 gene." (PMID 40964200, 2025). "Fructose‐1,6‐bisphosphatase (FBPase) deficiency, caused by an FBP1 mutation, is an autosomal recessively inherited metabolic disorder characterized by impaired gluconeogenesis." (PMID 38111981, 2024).
genetic disorder (1 paper, 2025). "The small number of cases with FBP1 deficiency identified during the neonatal period in our cohort likely indicates that this genetic disorder has a phenotypic spectrum broader than originally thought, with most subjects not experiencing any metabolic crises before their presenting episode." (PMID 41327277, 2025).
FBP1 also shares sentences with these, for which no sentence is quoted: kidney tumors (4 papers); fungal infections (3); gastric tumors (3); acute myeloid leukemia (2); COVID-19 (2); eosinophilia (2); Hepatic steatosis (2); sarcoma (2); T cell deficiency (2); acute kidney injury (1); atopic dermatitis (1); atrial fibrillation (1); bacterial infection (1); beta-ketothiolase deficiency (1); cervical squamous cell carcinoma (1); Cirrhosis (1); colorectal adenocarcinoma (1); congenital malformation syndromes (1); Cryptococcal meningitis (1); Failure to thrive (1); glucose metabolism disorder (1); glycogen storage diseases (1); Griscelli syndrome type 2 (1); head and neck squamous cell carcinoma (1); hemorrhoid (1); Immunodeficiency (1); invasive lobular carcinoma (1); Ketotic hypoglycemia (1); lung fibrosis (1); lymph node metastasis (1).
A further 17 diseases each share a sentence with FBP1 in 1 paper.